AAGAB (alpha and gamma adaptin binding protein)
Description:
May be involved in endocytic recycling of growth factor receptors such as EGFR.
Synonyms: FLJ11506; p34; KPPP1; PPKP1; PPKP1A
Tractability: PROTAC: ubiquitination databases record sites on it; its protein half-life has been measured.
Gene: Protein-coding gene on chromosome 15 (67,200,667 to 67,255,195, reverse strand). Ensembl gene ENSG00000103591.
Subcellular location: Cytoplasm, cytosol
Subcellular location (Human Protein Atlas): Cytosol; Nuclear speckles
Gene Ontology:
Molecular function: protein binding
Cellular component: cytoplasm; cytosol
Genetic constraint (gnomAD): Loss-of-function variants: 27 observed, 32.2 expected, observed/expected ratio (o/e) 0.84, 90% interval 0.62 to 1.16. The upper end of that interval is the gene's LOEUF score, 1.16, which puts it in group 5 of 6, group 1 being the genes least tolerant of losing a copy. Missense variants: 350 observed, 302.22 expected, observed/expected ratio (o/e) 1.16, 90% interval 1.06 to 1.26. Synonymous variants: 107 observed, 106.83 expected, observed/expected ratio (o/e) 1, 90% interval 0.86 to 1.18.
Homologues: Orthologues: chimpanzee AAGAB (99% identical), dog AAGAB (91% identical), rabbit AAGAB (90% identical), macaque AAGAB (87% identical), mouse Aagab (85% identical), rat Aagab (85% identical), pig AAGAB (79% identical), tropical clawed frog aagab (62% identical), guinea pig AAGAB (60% identical), zebrafish aagab (56% identical).
Diseases named in the same sentence as AAGAB in open-access papers:
AAGAB is named in the same sentence as 10 diseases in open-access papers, as found by Europe PMC text mining. Sharing a sentence is not in itself a finding about the gene and the disease. The quoted sentences say what the papers report.
breast carcinoma (3 papers, 2017 to 2023). "Clearly, further validation of the role of AAGAB in breast cancer is warranted and will be performed as new neoadjuvant chemotherapy datasets become available." (PMID 31200764, 2019). "The level of AAGAB was found to be prognostic of response (p < 0.001) in renal cancers (favourably) and in thyroid cancers (unfavourably) from the TCGA study, and expression is elevated in breast cancer, relative to the normal breast (p < 0.001)." (PMID 31200764, 2019). "However, the exact role of AAGAB in breast cancer is currently unclear and potentially warrants further investigation." (PMID 31200764, 2019). "Totally 15 breast cancer risks genes were obtained (Benjamini & Hochberg FDR < 0.05) and 6 of them (FAM84B, AAGAB, RPS25, SH3BP4, KRT80, TANK) showed the most significant correlation with the patient survival." (PMID 28621677, 2017). "In this study, a hypoxia-responsive circRNA, circAAGAB, derived from the alpha- and gamma-adaptin-binding protein p34 gene AAGAB, was identified in breast cancer MCF-7 cells by RNA sequencing, and the circular structure and expression levels under different oxygen concentrations were validated." (PMID 36899354, 2023).
Palmoplantar keratoderma (2 papers, 2019 to 2025). Abnormal thickening of the skin of the palms of the hands and the soles of the feet. "All participants with AAGAB variants presented with punctate palmoplantar keratoderma, showing a clear genotype-phenotype correlation." (PMID 39630431, 2025). "AAGAB has primarily been studied for its role in punctate palmoplantar keratoderma and the role of adaptin in the clathrin-independent endocytosis of epidermal growth factors." (PMID 31200764, 2019).
allergic disease (1 paper, 2017). An immune response that occurs following re-exposure to an innocuous antigen, and that requires the presence of existing antibodies against that antigen. "However, many have a known function that is directly relevant to allergic disease pathophysiology, such as F11R82, 83, MICB84, CD24785, 86, PGAP387, AAGAB,88CAMK489 and PEX1490." (PMID 29333270, 2017). "Some of these genes have a known function that is relevant to allergic disease, including F11R, CD247, PGAP3, AAGAB, CAMK4 and PEX14, and so could be prioritized for functional follow-up." (PMID 29333270, 2017).
punctate palmoplantar keratoderma type 1 (1 paper, 2025). Punctate palmoplantar keratoderma type I (PPKP1), also known as Buschke-Fischer-Brauer syndrome, is a very rare hereditary skin disease characterized by irregularly distributed epidermal hyperkeratosis of the palms and soles with wide variation among patients.. "Heterozygous mutations in AAGAB cause punctate palmoplantar keratoderma type 1, a skin disorder, and are associated with an increased incidence of cancer." (PMID 40938986, 2025).
cancer (3 papers, 2023 to 2025). A tumor composed of atypical neoplastic, often pleomorphic cells that invade other tissues. "In this study, it is worth mentioning that the AAGAB and SCYL2 expressions were lower in the cancer samples, but there were found to be risk factors through the Cox analysis." (PMID 37740762, 2023). "The TMEM251, AAGAB, ENTR1, SCYL2, and WDR72 were all found to be expressed mainly in cancer cells." (PMID 37740762, 2023).
tumor (1 paper, 2023). "However, as risk genes for poor prognosis, the AAGAB and the SCYL2 expressions were found to be decreased in the tumor tissues at both mRNA and protein levels." (PMID 37740762, 2023). "The AAGAB and the ENTR1 expressions showed significant differences in the different T stages and different tumor stages." (PMID 37740762, 2023).
AAGAB also shares sentences with these, for which no sentence is quoted: cardiomyopathy (1 paper); renal carcinoma (1); skin disorder (1); thyroid cancer (1).